IL18 (interleukin 18)
Diseases named in the same sentence as IL18 in open-access papers (continued):
Sharing a sentence is not in itself a finding about the gene and the disease.
heart disease (15 papers, 2013 to 2025). "We conducted a preliminary gene expression screen for diverse genes implicated in heart disease tissue damage which first identified pro-inflammatory cytokine Interleukin 18 (Il18)." (PMID 23658656, 2013). "Activated caspase-1 catalyzes the processing of interleukin-1β and interleukin-18 precursors into their active forms to stimulate the inflammatory response in heart diseases." (PMID 40149903, 2025). "Interleukin-18-binding protein, (IL-18) is a member of the IL-1 family of cytokines and increasing numbers of clinical studies indicate a role for IL-18 in heart diseases." (PMID 36720768, 2023). "In this review, the pathophysiological effects of interleukins including the IL-1 family (IL-1, IL-18, IL-33, and IL-37), IL-2, IL-4, the IL-6 family (IL-6 and IL-11), IL-8, IL-10, and IL-17 on primary cell types of heart disease is elucidated." (PMID 37047468, 2023). "Overall, the role of IL-18 in heart disease is primarily in amplifying myocardial dysfunction, and the level also was recognized as a marker of heart injury in patients." (PMID 37047468, 2023). "The expressions of pyroptosis-related NLRP3, GSDMD, caspase-1, IL-1β, and IL-18 in these heart disease patients were elevated." (PMID 35647057, 2022). "Several inflammatory cytokines, such as TNFα, the IL-1 family, IL-6, IL-8, IL-10, IL-18, and IFNα have also been shown to play a pathological role in various heart diseases." (PMID 35069538, 2021). "Previous studies also suggest that either mRNA or protein levels of IL-18 are enhanced in heart disease and heart infarction, and that IL-18 or IL-1β play a significant role in myocardial injury." (PMID 32503314, 2020). "This review will primarily focus on the pathophysiological effects of various interleukins including the IL-1 family (IL-1, IL-18, IL-33, IL-37), IL-2, IL-4, the IL-6 family (IL-6 and IL-11), IL-8, IL-10, IL-17 on primary cells of heart disease-CMs, FBs, ECs, and immune cells." (PMID 37047468, 2023). "IL-18 is a proinflammatory cytokine produced during various heart diseases." (PMID 37047468, 2023). "In summary, these studies demonstrate a role for IL-18 in heart disease." (PMID 24115947, 2013). "Increasing numbers of animal and clinical studies indicate a role for IL-18 in heart disease." (PMID 24115947, 2013). "Regardless of a viral, autoimmune, or chemotherapy-induced trigger, many inflammatory cardiac diseases converge on NLRP3 activation and the release of pro-inflammatory cytokines such as IL-1β and IL-18." (PMID 40940808, 2025). "The role of IL-18 in different types of heart disease is not consistent and is even controversial." (PMID 37047468, 2023).
kidney (15 papers, 2014 to 2025). "Several primary renal diseases and systemic diseases affecting the kidney are associated with NLRP3 inflammasome/IL-1β/IL-18 axis activation." (PMID 24450291, 2014). "IL-18 is an important mediator in ischemic kidney injury that promotes leukocyte infiltration to kidney parenchyma, and it is correlated with the severity of proteinuria." (PMID 31018558, 2019). "Both DyBN and DyNA suggested a reduced role of IL-18 and increased role of IL-1RA with MP, along with increased liver damage with CSP." (PMID 27867357, 2016). "In conclusion, our results verify the reno-protective potential of AEA against HgCl2-induced kidney injury by its anti-inflammatory, antioxidant, and anti-apoptotic capacities by modulating WNT-5A/BCL-2, IP3/NFATC1, HMGB-1/RAGE/NF-κB, caspase-1/IL-18, and caspase-3/BCL-2 cues." (PMID 37488162, 2023). "IL-18 is a proinflammatory cytokine (known as IFN-γ inducing factor), increased the levels of circulating inflammatory cytokines such as TNF-α and IFN-γ in the presence of stimuli and resulted in a worsening of the acute kidney injury, and further damage to renal function." (PMID 32824088, 2020). "However, the KIM-1 decrease correlated with a GFR decrease as well as an IL-18 decrease; thus, the results suggest that these parameters could not be used in assessing kidney injuries induced by RLT." (PMID 37108668, 2023).
immune diseases (14 papers, 2009 to 2024). "IL-1β and IL-18 are pro-inflammatory cytokines that cause complex immune diseases." (PMID 35042538, 2022). "Other immune dysfunctions that were observed included alterations in both pro- and anti-inflammatory markers (IL-18, IL-10, and IFN- γ)." (PMID 32691839, 2020). "IL18 is a proinflammatory cytokine with important functions, such as induction of angiogenesis and regulation of immune function, and is involved in the progress of many inflammatory diseases, immune disorders, and tumors." (PMID 36591509, 2022). "So, these variations may influence the biological function of VDR/VEGF/IL-18/MBL, result in immune dysfunction, cause chronic inflammatory hepatocellular injury, and ultimately confer susceptibility to HCC." (PMID 31830994, 2019). "Both endogenous and exogenous IL-37 have been shown to ameliorate inflammation and regulate immune disorder via inhibiting the production of inflammatory mediators including IFN-γ, TNF-α, IL-6, and IL-18." (PMID 28781417, 2017). "Some IRPs in cluster 7, such as CXCL11, CXCL9, TNF, CXCL10, and IL18, are closely associated with HIV-1 disease progression and immune disorders, irrespective of whether patients received ART treatment." (PMID 36408648, 2023).
psychiatric disorder (10 papers, 2011 to 2024). A disorder characterized by behavioral and/or psychological abnormalities, often accompanied by physical symptoms. "In conclusion, we investigated the effects of IL-18 deficiency on the central nervous system and its association with psychiatric disorders." (PMID 34708129, 2021). "In sum, these immune-related molecular changes suggest that an IL-18 deficiency causes the abnormal activation of immune pathways and affects neural plasticity, leading to psychiatric disorders such as MDD and AD, though other inflammatory factors should be considered." (PMID 34708129, 2021). "In numerous psychiatric disorders, elevated levels of IL-1 and IL-18 serve as indicators for the activation of the NLRP3 inflammasome." (PMID 38026692, 2023). "Later, the axis of Alu-IL-18/IL-1β was activated and inflammation was triggered aggravating the progression and development of psychiatric disorders, in turn." (PMID 32038328, 2019). "However, enhancement in the expression of IL-1β and IL-18 in psychiatric disorders by Alu is still unclear." (PMID 32038328, 2019). "Elevation of IL-18 has been reported for rodents and humans with psychiatric disorders." (PMID 21799730, 2011). "CRP and many serum cytokines levels have been recently suggested as biological biomarkers of psychiatric diseases and skin diseases such as TNF-α, IL-1β, IL-6, and IL-18." (PMID 39624485, 2024).
respiratory disease (7 papers, 2013 to 2025). "NLRP3-induced inflammation and the release of IL-1β and IL-18 are linked to various respiratory diseases." (PMID 40218944, 2025). "Both IL-18 and TNFα have been proposed as potential diagnostic and prognostic biomarker for the pathogenesis of respiratory disease." (PMID 37243736, 2023). "Altogether, all the pieces of evidence demonstrate an important role of IL-18 in severe forms of respiratory diseases and the pertinency of anti-IL-1R7 in treating IL-18-mediated respiratory inflammation." (PMID 38983847, 2024). "Moreover, in another respiratory disease SARS, caused by SARS-CoV-1 virus, IL-18 concentration was also elevated in the patients than those in healthy subjects, and higher levels were observed in nonsurvivors than survivors." (PMID 38983847, 2024). "Despite this, it is clear that early innate immune responses of airway epithelial cells constitute an important component of first line of defense against respiratory disease, and, compatible with our data, lung epithelial cells can secrete IL-1β and IL-18 to induce the inflammatory response." (PMID 30978238, 2019).
hematologic disorder (6 papers, 2016 to 2024). A disease involving the hematopoietic system. "Adoptive cellular therapy (ACT) using memory-like (ML) natural killer (NK) cells, generated through overnight ex vivo activation with IL-12, IL-15, and IL-18, has shown promise for treating hematologic malignancies." (PMID 38960949, 2024). "In our study the relationship of serum level of IL-18 and involvement of different organs (such as kidneys, CNS, heart, and hematologic disorders) was found." (PMID 27047807, 2016). "As described in other hematological malignancies and diseases characterized by accentuated fibrosis, we hypothesize that IL-18 may contribute to tumorigenesis and BM fibrosis process in MPN." (PMID 34084749, 2021).
adenocarcinoma (4 papers, 2024 to 2025). A common cancer characterized by the presence of malignant glandular cells. "In addition, studies have shown that the overexpression of miR-223 in human adenocarcinoma alveolar basal epithelial cells can reduce LPS-induced Caspase-1, IL-1β, and IL-18 levels by targeting NLRP3." (PMID 38448875, 2024).
colon polyp (4 papers, 2013 to 2024). "IL-18−/− and IL-18r−/− mice were more susceptible to colon polyp formation and treatment of caspase-1−/− mice with recombinant IL-18 leads to amelioration of disease." (PMID 24273542, 2013). "The three highest-ranked causal circulatory cytokines for colonic polyp were: MIP1b (MIP = 0.752, MACE = −0.033), IL-6 (MIP = 0.196, MACE = −0.012), IL-18 (MIP = 0.112, MACE = 0.004)." (PMID 39439893, 2024). "The role of IL-18 in intestinal disease is largely related to its activity in regulating proinflammatory responses." (PMID 35842726, 2022).
inflammatory myopathies (4 papers, 2018 to 2024). "IL-18 is expressed in skeletal muscle and high expression of IL-18 has been reported in skeletal muscle in inflammatory diseases such as inflammatory myopathies and COPD." (PMID 29342149, 2018). "The level of IL18 was elevated in patients with inflammatory myopathy." (PMID 35517781, 2022). "To further explore the expression of the receptors for the 8 differentially expressed cytokines (Eotaxin, IL7, IL18, IP10, MCP1, MCSF, MIG and SCGFβ) in inflammatory myopathy, we used the ligand-receptor database (ramilowski_pairs) in the R package celltalker." (PMID 35517781, 2022).
brain disease (3 papers, 2014 to 2024). "Inhibiting the activation of NF-κB signals in microglia and neurons observably mitigate neuroinflammation in brain disease, manifested by down-regulation of pro-inflammatory mediators, such as IL-6, IL-18, iNOS and COX-2, and the loss of neurons." (PMID 37600790, 2023). "Induction of inflammasomes causes cleavage and release of IL-1β and IL-18, representing pathogenic processes that underlie inflammatory diseases although their contribution HIV-associated brain disease is unknown." (PMID 24886384, 2014).
retinopathy (3 papers, 2019 to 2024). "IL-18 was significantly upregulated in the serum from patients with Diabetes Mellitus Type 2 with background retinopathy, with the serum inducing a higher rate of neovascularisation when injected intradermally to mouse skin samples (mouse cutaneous angiogenesis test) compared to control serum." (PMID 31379825, 2019).
heart (1 paper, 2015). "They measured urinary levels of few novel biomarkers (neutrophil gelatinase-associated lipocalin (NGAL), interleukin-18 (IL-18), kidney injury molecule-1 (KIM-1), and cystatin C) pre- and postoperatively in infants younger than 6 months of age to predict outcomes following congenital heart surgery." (PMID 26697493, 2015).
IL18 also shares sentences with these, for which no sentence is quoted: acute myocardial infarction (13 papers); chronic periodontitis (12); Allergy (8); septic shock (8); vasculitis (8); esophageal cancer (6); brain injury (5); polymyositis (5); esophageal squamous cell carcinoma (4); liver (4); Shock (4); ST Elevation Myocardial Infarction (4); viral diseases (4); bipolar disorder (3); genetic diseases (3); heart rhythm disorders (3); leukopenia (3); Onset (3); pericarditis (3); Primary immunodeficiency (3); retinal vein occlusion (3); stomach cancer (3); thromboses (3); thyroid (3); acute respiratory failure (2); alopecia areata (2); autism spectrum disorder (2); autoimmune lymphoproliferative syndrome (2); bacterial pneumonia (2); benign ovarian tumors (2).
A further 213 diseases each share a sentence with IL18 in 2 papers or fewer.